RNU6-505P (RNA, U6 small nuclear 505, pseudogene)
Gene: Small nuclear RNA gene on chromosome 3 (146,996,607 to 146,996,713, reverse strand). Ensembl gene ENSG00000207156.
Homologues: Orthologues: chimpanzee U6 (99% identical), pig U6 (80% identical), rat LOC120095713 (70% identical), mouse Gm26369 (63% identical). Paralogues in human: RNU6-338P (89% identical), RNU6-1011P (88% identical), RNU6-1124P (88% identical), RNU6-116P (87% identical), RNU6-1075P (86% identical), RNU6-12P (86% identical), RNU6-13P (86% identical), RNU6-140P (86% identical), RNU6-187P (86% identical), RNU6-19P (86% identical), RNU6-25P (86% identical), RNU6-29P (86% identical), and 1288 more.